TRIM28 (tripartite motif containing 28)
Diseases named in the same sentence as TRIM28 in open-access papers (continued):
Sharing a sentence is not in itself a finding about the gene and the disease.
food allergy (1 paper, 2022). Gastrointestinal disturbances, skin eruptions, or shock due to allergic reactions to allergens in food. "Given the influence of HERVs and of TRIM28 and SETDB1 on innate and adaptive immune responses, their transcriptional activation in children with food allergies suggest that they might play important roles in the development of these diseases." (PMID 35344298, 2022).
herpesvirus infections (1 paper, 2022). "In herpesvirus infections, TRIM28 phosphorylation either on serine 473 or 824 triggers the lytic gene expression of latent cytomegalovirus and Epstein-Barr virus." (PMID 35350437, 2022).
Impaired glucose tolerance (1 paper, 2014). An abnormal resistance to glucose, i.e., a reduction in the ability to maintain glucose levels in the blood stream within normal limits following oral or intravenous administration of glucose. "This latter study also revealed a high predisposition of female Trim28 heterozygous mice to impaired glucose tolerance." (PMID 24884990, 2014).
kidney cancer (1 paper, 2023). Primary or metastatic malignant neoplasm involving the kidney. "Intrigued by the genetic evidence of TRIM28 loss of function in kidney malignancy, we set out to investigate the role of TRIMI28 in kidney cancer in this study." (PMID 36935008, 2023). "In this study, we show TRIM28 retards kidney cancer cell proliferation through inhibiting autophagy." (PMID 36935008, 2023). "We first examined the relation between TRIM28 and RCC patient survival with kidney cancer datasets from the Clinical Proteomic Tumor Analysis Consortium (CPTAC) and The Cancer Genome Atlas (TCGA) projects." (PMID 36935008, 2023).
liver diseases (1 paper, 2024). "In addition, chronic HCV infection is one of the main causes of liver diseases, where TRIM28 modulates viral replication and particle aggregation, may contribute to the chronicity of infection at these critical stages." (PMID 39534556, 2024). "The interaction between TRIM28 and HBX is particularly important in the context of HBV‐induced liver diseases, including chronic hepatitis, liver cirrhosis, and HCC." (PMID 39534556, 2024).
liver fibrosis (1 paper, 2024). "Some can play the same role in the face of the same disease, such as TRIM28 and TRIM38 in the progression of MAFLD and TRIM15 and TRIM47 in liver fibrosis." (PMID 39199424, 2024).
Lupus (1 paper, 2026). "Lupus patients showed reduced TRIM28 and increased SETDB1 expression, consistent with altered regulation of HERV repression pathways." (PMID 41828687, 2026).
metabolic syndrome (1 paper, 2010). A cluster of metabolic risk factors for CARDIOVASCULAR DISEASES and TYPE 2 DIABETES MELLITUS. "Taken together, these results show that mice with a half dosage of Trim28 are predisposed to metabolic syndrome." (PMID 21092094, 2010). "Trim28 mutants additionally develop metabolic syndrome and abnormal behavior with incomplete penetrance." (PMID 21092094, 2010). "Some isogenic littermates do not display this phenotype, demonstrating a significant degree of stochasticity in the development of metabolic syndrome in Trim28 heterozygous mutants." (PMID 21092094, 2010).
progressive supranuclear palsy (1 paper, 2016). A rare late-onset neurodegenerative disease characterized by supranuclear gaze palsy, postural instability, progressive rigidity, and mild dementia. "We therefore obtained post-mortem tissue from individuals who had had PDD, AD, or progressive supranuclear palsy (PSP), along with age-matched controls, and examined the biochemical distribution of TRIM28." (PMID 27779468, 2016).
prostate adenocarcinoma (1 paper, 2017). "We have highlighted known and novel drivers of prostate adenocarcinoma, suggesting further investigation into the role of KAT2A and TRIM28 in carcinogenesis." (PMID 28592290, 2017).
proteinopathy (1 paper, 2016). "Based on studies showing that reducing disease protein levels can rescue neurodegeneration in other proteinopathy models, we tested whether decreasing TRIM28 would mitigate the phenotypes resulting from overexpression of either α-Syn or tau." (PMID 27779468, 2016).
RSV bronchiolitis (1 paper, 2023). "No study has explored the expression of HERVs, TRIM28, and SETDB1 during RSV bronchiolitis." (PMID 36826024, 2023).
cancer (129 papers, 2008 to 2026). A tumor composed of atypical neoplastic, often pleomorphic cells that invade other tissues. "By interrogating TRIM28 transcriptome using Cancer Hallmark signature, we nominated E2F Target as the most significant hallmark induced by TRIM28." (PMID 40519166, 2025). "TRIM28 is a transcriptional co‐suppressor and is associated with tumor suppression and carcinogenicity in various cancers." (PMID 41194971, 2025). "TRIM28, an overexpressed protein in cancers linked to poor prognosis, binds to regulatory elements in Bok mRNA, promoting its degradation." (PMID 40841912, 2025). "Specific genes commonly affected by ERK inhibition and TBK1–IKKε inhibition such as TRIM28 have been linked with stem cells and other cancer-associated mechanisms." (PMID 40738190, 2025). "Aberrant overexpression of TRIM28 is frequently observed in human cancers and associated with aggressive clinical features and poorer survival of patients in many cancers, including liver and ovarian cancer." (PMID 39532800, 2024). "Aberrant overexpression of TRIM28 is frequently observed in multiple human cancers and associated with poorer survival of patients, indicating that it plays a critical role in malignant tumor progression." (PMID 39532800, 2024). "XAF1 expression is inversely correlated with TRIM28 expression in cancer cell lines and tumor tissues and more tightly associated with the survival of TRIM28-high versus TRIM28-low patients." (PMID 39532800, 2024). "In the current study, we observed that TRIM28 elevation is associated with abnormal reduction of XAF1 in cancer cell lines and tumor tissues." (PMID 39532800, 2024). "Our analysis of the Sequence Read Archive (SRA), Gene Expression Omnibus (GEO), and Asian Cancer Research Group (ACRG) databases showed that TRIM28 is positively associated with PD-L1, TBK1, and IRF1 at the transcriptional level." (PMID 37357254, 2023). "Second, the effects of TRIM28 on different cancers are heterogeneous, and the causes of this heterogeneity should be further identified to help provide accurate and personalized cancer treatment." (PMID 37781084, 2023). "While a loss of function TRIM28 mutations are rarely observed in human tumors, its expression levels are increased in many types of human cancer." (PMID 37070200, 2023). "Based on this evidence, it appears that immune infiltration influences cancer progression caused by TRIM28, since we found that TRIM28 was mainly expressed in monocytes/macrophages." (PMID 37781084, 2023). "Although TRIM28 is rarely mutated in human cancers, its expression is often deregulated with overexpression being linked to poor survival." (PMID 37070200, 2023). "RIPK3 activation causes cancer cells to exhibit TRIM28 derepression and improves the anti-tumor microenvironment." (PMID 36267408, 2022). "TRIM28 expression is upregulated in cancer including LC, which is also implicated in drug resistance." (PMID 36476351, 2022). "One established function of TRIM28 is silencing the endogenous retrovirus elements by recruiting other epigenetic machinery, which is associated with cancer." (PMID 35201498, 2021). "As the epigenetic factor modulating chromatin structure, TRIM28 regulates the expression of numerous genes and is associated with progression and poor prognosis in many types of cancer." (PMID 34440702, 2021). "Altogether, our results demonstrated that TRIM28 affects the expression of the genes implicated in the pathways common for stem cells and cancer cells." (PMID 34440702, 2021). "Our results demonstrate that the association between high TRIM28 expression and an enriched cancer stem cell-like phenotype is a common phenomenon across solid tumors." (PMID 33810347, 2021). "Altogether, this strongly supports the previously reported association between TRIM28 and cancer stemness." (PMID 33810347, 2021).
cancer (continued). "This suggests association of TRIM28 expression with GSCs, homing to the core of the tumour and corroborated with the previous report on altered cancer stem cell marker profile in GB core vs. rim." (PMID 34500575, 2021). "Here, we analyzed the profile of transcription factors significantly associated with the upregulation of TRIM28 to verify the potential mechanism of cancer stemness acquisition." (PMID 33076560, 2020). "From a clinical perspective, establishing if the penetrance of TRIM28 mutations is influenced by the parent-of-origin of the mutation is important, because this would have considerable impact on cancer risks and genetic counselling." (PMID 30885698, 2019). "We next sought to understand the underlying molecular interplay associated with TRIM28 expression ratios and signaling pathways linked to cancer." (PMID 29631612, 2018). "Recent studies revealed the elevated TRIM28 expression in different types of tumors, and moreover, high levels of TRIM28 expression are associated with aggressive clinical features and poor prognosis in most types of cancers." (PMID 30309319, 2018). "In summary, we identify TRIM28 as an E3 ubiquitin ligase of FBP1.MAGE-A3 and MAGE-C2 can bind with TRIM28 to form MAGE-TRIM28 cancer-associated ubiquitin ligase in HCC." (PMID 28394358, 2017). "Loss of function of TRIM28 leads to dysregulation of cell cycle, cellular response to stress, cancer cell metabolism, and inhibition of oxidative phosphorylation." (PMID 27845900, 2017). "In our data we observed significant upregulation of AMPK protein level in TRIM28-depleted xenografts, suggesting loss of function of cancer-specific TRIM28-MAGE-A3/6 ubiquitinase." (PMID 27845900, 2017). "Herein we examine Trim28's role in the epithelial-to-mesenchymal transition (EMT) which is strongly implicated in cancer metastasis." (PMID 24983967, 2014). "Therefore, we believe that it is necessary to study cancer-related mutations of TRIM28, which can further clarify its clinical significance." (PMID 39100077, 2024). "The association of TRIM28 with various cancers through signaling pathways." (PMID 39534556, 2024). "High expression of TRIM28 is positively associated with poor prognosis in some cancers." (PMID 36756159, 2023). "Furthermore, KEGG pathway analysis revealed that TRIM28 regulates several cancer-associated pathways such as the PI3K-AKT, TNF, and PPAR pathways." (PMID 37357254, 2023). "Our results suggested that TRIM28 is significantly associated with cancer prognosis and immunity." (PMID 37781084, 2023). "Interestingly, our results from TIMER2.0 analysis revealed a significant association between TRIM28 expression and MDSCs infiltration across various cancer types." (PMID 37865804, 2023). "Higher TRIM28 gene expression has been linked to a more aggressive disease in several types of cancers and is associated with poor prognosis, suggesting that TRIM28 oligomerization could be contributing to tumorigenesis." (PMID 37070200, 2023). "We analyzed the OS, DFI, DSS, and PFI probabilities across cancers to determine whether TRIM28 expression is linked to cancer prognosis." (PMID 37781084, 2023). "Moreover, TRIM28 affected a wide range of cancer-related scores, and the abnormal expression of TRIM28 was also involved in tumor mutational burden, drug sensitivity, and microsatellite instability in cancer." (PMID 37781084, 2023). "TRIM28 is overexpressed in various cancers in which it is associated with poor prognosis." (PMID 33043006, 2020). "Taken together, we speculate that TRIM28 may be a ripe target underlying the interaction of ethanol and inflammation with cancer risk in the gastrointestinal tract." (PMID 29481576, 2018). "Higher TRIM28 gene expression has been linked to prometastatic cervival cancer." (PMID 28851455, 2017). "In addition, TRIM28 has different mutations in various types of cancers, mainly missense mutations." (PMID 39100077, 2024).
cancer (continued). "However, in the group of cancer patients with high TRIM28 expression, higher levels of MDSCs were associated with worse patient survival, suggesting that elevated TRIM28 levels might enhance the immune-suppressive effect of MDSCs." (PMID 37865804, 2023). "However, how loss of ZFP57 or TRIM28 function is related to extensive hypomethylation in imprinted loci in cancer cells is currently unknown." (PMID 26473022, 2015). "Consistently, high Bok and low TRIM28 levels correlate with increased survival in cancers like HCC and kidney cancer, further supporting Bok’s role as a tumor suppressor despite its pro-tumorigenic role in KRAS-driven lung cancer." (PMID 40841912, 2025). "The identification of TRIM28 as a combination therapy target illustrates the transferability of iPANDDA’s methodology, offering a template for similar analyses in other cancers." (PMID 41388088, 2025). "Concomitantly, proliferative cascades such as EGFR, PI3K, and MAPK were uniformly downregulated, which is consistent with reports describing TRIM28 as a positive regulator of cell cycle progression and growth factor–mediated proliferation in various cancers." (PMID 41303350, 2025). "TRIM28 exhibits a multifaceted role in cancer pathogenesis by regulating diverse signaling pathways implicated in cell proliferation, survival, and genomic stability." (PMID 39534556, 2024). "The dual role of TRIM28 in gene regulation and DNA repair highlights its critical function in cellular homeostasis and its potential as a therapeutic target in cancer." (PMID 39534556, 2024). "This action promotes the proliferation of cancer cells both in laboratory settings and in a murine model, indicating a significant role for TRIM28 in promoting tumor growth." (PMID 39534556, 2024). "Numerous studies suggest that TRIM28 is involved in cancer signaling pathways, particularly in promoting cell proliferation, immune evasion, inflammation, invasion and migration, and evasion of apoptosis." (PMID 39100077, 2024). "By deepening our understanding of TRIM28’s functions and interactions, we can potentially uncover innovative treatment options that harness its capabilities to combat cancer more effectively and enhance patient outcomes." (PMID 39534556, 2024). "By uncovering TRIM28’s complex roles across different cancers and other diseases, this review underscores its potential as a therapeutic target." (PMID 39534556, 2024). "Although TRIM28 is highly expressed in various cancer tissues and has oncogenic effects, there are still a few studies indicating that TRIM28 has certain anticancer effects." (PMID 39100077, 2024). "We sought to understand how MAGEC2 specifically recognizes TRIM28 as this will provide a strategy to target MAGEC2 in various cancer therapeutics." (PMID 38448672, 2024). "The significance of TRIM28 as a versatile regulator opens the door to innovative therapeutic strategies, particularly in cancer treatment and the management of other diseases." (PMID 39534556, 2024). "In this paper, we not only conducted a bioinformatics analysis and examined the relationship between TRIM28 and cellular processes in health and disease, particularly in cancer, but also provided a valuable update on this subject." (PMID 39534556, 2024). "Its involvement in various pathways, including those regulating cell cycle progression, apoptosis, and response to genotoxic stress, makes TRIM28 a critical player in cancer biology and a potential target for therapeutic intervention." (PMID 39534556, 2024).